VWF (von Willebrand factor)
Diseases named in the same sentence as VWF in open-access papers (continued):
Sharing a sentence is not in itself a finding about the gene and the disease.
lung adenocarcinoma (6 papers, 2017 to 2025). A carcinoma that arises from the lung and is characterized by the presence of malignant glandular epithelial cells. "Somewhat contrary to these findings, a more recent (albeit low powered) study demonstrated that VWF upregulation may be associated with a favorable prognosis in lung adenocarcinoma." (PMID 35327035, 2022). "In lung adenocarcinoma, von Willebrand factor (vWF), a multifunctional glycoprotein, inhibits angiogenesis by regulating angiopoietin-2 and integrin αvβ3." (PMID 41560752, 2025). "Additionally, the level of VWF can serve as a biomarker for the early diagnosis of liver cancer and lung adenocarcinoma." (PMID 37953280, 2023). "The special molecular mechanism of how VWF affects lung adenocarcinoma is still underway." (PMID 33968738, 2021). "We next examined a mouse lung adenocarcinoma model for vWF expression." (PMID 29299165, 2017). "Curiously, the capillaries of lung squamous cell carcinomas (LSCC) have little vWF expression and are not proliferative or migratory, suggesting that a correlative relationship may exist between the expression of vWF and the pro-angiogenic potential of ECs in lung adenocarcinoma." (PMID 29299165, 2017).
Macrothrombocytopenia (6 papers, 2013 to 2025). "It has been associated with macrothrombocytopenia, spontaneous platelet clumping, mucocutaneous, and other bleeding, which can be largely prevented by von Willebrand factor (VWF) concentrate infusion." (PMID 37735203, 2023). "These patients have a VWF gain-of-function mutation and therefore an enhanced binding of GPIb to VWF associated with a transient macrothrombocytopenia." (PMID 35366951, 2022).
metastatic disease (6 papers, 2012 to 2024). "Comparing metastatic tumors with the primary solid tumor, there was a strong correlation between metastatic tumors and the multimeric uncleaved vWF in blood plasma." (PMID 24213506, 2012). "Moreover, studies have detected higher levels of plasma VWF in metastatic disease compared to primary cancer presentations." (PMID 33571850, 2021). "Importantly, these high VWF levels correlate with presence of metastatic disease and poorer prognosis." (PMID 33571850, 2021). "Intriguingly, patients with metastatic disease have unusually large VWF multimers." (PMID 33571850, 2021). "Interestingly, patients with metastatic disease have 165% more ultra-large VWF compared to patients with localised tumours (p<0.001)." (PMID 33571850, 2021). "Four BD proteins, including PZ, AZGP1, SHBG, and VWF, were selected for further testing by ELISA using a cohort of 52 PDAC patients, including 19 stage III and 33 stage IV with metastatic disease." (PMID 31346328, 2019).
periodontitis (6 papers, 2010 to 2024). An acute or chronic inflammatory process that affects the tissues that surround and support the teeth. "SERPINA1, ERLEC1, and VWF showed high diagnostic values (AUC > 0.85), so they were considered as potential biomarkers for periodontitis." (PMID 36072904, 2022). "After adjustment for covariates, there was strong evidence for an association between PISA and vWF, but the associations between periodontitis one the one hand with CRP and HDL-c levels seen in the groupwise analysis did not persist after adjusting for confounders." (PMID 39212739, 2024). "Additionally, periodontitis is associated with higher levels of other inflammatory serum biomarkers including von Willebrand factor (vWF), fibrinogen, and endothelial progenitors' cells." (PMID 33521070, 2020). "Several blood cell components, including erythrocyte sedimentation rate (ESR), C-reactive protein (CRP), interleukin-6 (IL-6), fibrinogen, Von Willebrand factor, and thrombocytes, have been studied in connection with periodontitis." (PMID 38595889, 2024). "Three ERS-related genes, SERPINA1, ERLEC1, and VWF, showed valuable biomarker potential for periodontitis, which provide a target base for future studies on early diagnosis and treatment of periodontitis." (PMID 36072904, 2022). "After further screening by the validation set, SERPINA1, ERLEC1, and VWF were selected as potential biomarkers of periodontitis." (PMID 36072904, 2022). "A study with 63 participants confirmed that VWF in peripheral blood was higher in patients with periodontitis than in controls." (PMID 36072904, 2022). "Lastly, further studies are required to determine the location of SERPINA1, ERLEC1, and VWF in ERS and investigate the mechanisms by which these three genes are linked to periodontitis." (PMID 36072904, 2022). "The main finding of the current study was that in patients affected by periodontitis, in the multivariate analysis levels of IgG against Aa correlated with levels of vWF after correction and including several other potential confounding factors." (PMID 21050426, 2010). "In periodontitis patients, body mass index and anti-Aa IgG showed a positive correlation with vWF (β = 0.297, p = 0.010 and β = 0.248, p = 0.033 respectively)." (PMID 21050426, 2010). "In our previous study we observed elevated plasma levels of PAI-1 and vWF in periodontitis patients." (PMID 21050426, 2010). "VWF levels are associated with periodontitis severity; they do not improve after full-mouth extraction." (PMID 39212739, 2024). "However, VWF, as a marker of inflammation, remains to be investigated further in periodontitis." (PMID 36072904, 2022). "Therefore, SERPINA1, ERLEC1, and VWF were selected as potential biomarkers of periodontitis." (PMID 36072904, 2022). "A case–control study evaluated a series of thrombotic markers in patients with periodontitis, including PAI‐1, VWF, prothrombin cleavage fragments, and D‐dimer." (PMID 39494478, 2024). "Extensive research has explored the connections between periodontitis and various blood cell components, including ESR, CRP, IL-6, fibrinogen, Von Willebrand factor, and thrombocytes." (PMID 38595889, 2024). "Through machine learning, we identified three potential biomarkers of periodontitis, SERPINA1, ERLEC1, and VWF and found strong correlations between these ERS-related genes and immune cell infiltration." (PMID 36072904, 2022). "Periodontitis patients showed higher levels of PAI-1 in comparison to controls (p = 0.009); they also showed higher values for vWF and F1+2 and lower values for D-dimer, but the differences were not statistically significant." (PMID 21050426, 2010). "In our study, SERPINA1 was the core gene in PPI and correlated with seven ERS-related genes including ERLEC1, VWF, EDEM2, DERL3, APOE, IL6, and CXCL8, suggesting that SERPINA1 may play an essential role in the pathological process of periodontitis." (PMID 36072904, 2022).
periodontitis (continued). "In a previous study, our group showed that systemically healthy periodontitis patients, in comparison to subjects without periodontitis, displayed higher levels of 2 markers of prothrombotic state, PAI-1 and vWF." (PMID 21050426, 2010).
Renal insufficiency (6 papers, 2011 to 2024). A reduction in the level of performance of the kidneys in areas of function comprising the concentration of urine, removal of wastes, the maintenance of electrolyte balance, homeostasis of blood pressure, and calcium metabolism. "Furthermore, hemostatic dysfunction including decreased glycoprotein IIb and IIIa levels, reduced von Willebrand factor activity, and altered arachidonic acid metabolism were detected in older individuals with renal insufficiency." (PMID 35629177, 2022).
schizophrenia (6 papers, 2013 to 2020). A major psychotic disorder characterized by abnormalities in the perception or expression of reality. "Some of these proteins such as Factor VII, vWF, CgA, AAT and IL-6r have also been found to be altered or predict development of schizophrenia in ultra-high risk or pre-onset individuals." (PMID 28974776, 2017). "However, to our knowledge only SNPs associated with IL-6r, CgA, vWF and AAT have previously been reported in schizophrenia." (PMID 28974776, 2017). "The objective of the present study was to test if physical functional capacity in patients with schizophrenia correlates with common inflammatory markers, such as CRP and Von Willebrand factor (VWF)." (PMID 27547191, 2016).
thrombocytopenic purpura (6 papers, 2020 to 2025). Purpura associated with a reduction in circulating blood platelets which can result from a variety of factors. "The most severe deficiency (<10% of the reference values) of ADAMTS-13 occurs in thrombocytopenic purpura, a condition characterized by large VWF multimer sizes and, consequently, an increased risk of thrombosis." (PMID 35215805, 2022). "Thrombocytopenic purpura (TTP) is a rare, potentially fatal pathology characterized by microangiopathic thrombotic syndrome and caused by an acute protease deficiency of von Willebrand factor, ADAMTS13." (PMID 35885465, 2022). "Others go on to describe an imbalance between von Willebrand Factor and ADAMTS-13 axis mirroring pathology similar to thrombocytopenic purpura." (PMID 35355577, 2022).
von Willebrand disease type 2A (6 papers, 2017 to 2025). "As observed for the patients in the ECMO group in this study, the loss of large vWF multimers is one of the hallmarks of von Willebrand disease type 2 A." (PMID 38822325, 2024). "Therefore, a genetic disorder that causes the loss of VWF high molecular weight multimers leads to a hemostatic disorder classified as von Willebrand disease type 2A." (PMID 38268521, 2024). "Usually, patients with von Willebrand disease type 2 A show low vWF; Ag, vWF: Rco < 30 IU/dL (30%), and vWF: Rco/vWF: Ag ratio < 0.6." (PMID 38822325, 2024). "In comparison, for the diagnosis of hereditary von Willebrand disease type 2A, the ratio of VWF Ristocetin co-factor activity (VWF:RCo) to the VWF antigen level (VWF:Ag) of less than 0.7 [5,] or 0.6 is used for the diagnosis." (PMID 38268521, 2024). "Thus, in a widely used guideline, VWF:RCo/VWF:Ag of <0.7 is used as a marker of von Willebrand disease type 2A." (PMID 38268521, 2024). "Simultaneously, a hematology consultation was requested, and hematological tests were performed—von Willebrand factor (vWF) antigen, factor VIII (fVIII), vWF ristocetin cofactor activity (vWF/Rco), and the vWF antigen/Rco ratio—leading to the diagnosis of von Willebrand disease type 2A." (PMID 40283648, 2025).
-infarcts (5 papers, 2018 to 2025). "Knockdown of ZFAS1 remarkably improved cardiac function via decreasing infarction ratio and increasing vWF expression, left ventricular ejection fraction, and left ventricular fractional shortening compared with group MI." (PMID 33952724, 2021). "In this study, the angiogenesis in the peri-infarction region was analyzed by immunostaining with Von Willebrand factor (vWF), an endothelial cell marker." (PMID 29760720, 2018). "However, after simultaneous treatment with XAV939, significant increase of infarction ratio, and decrease of vWF, LVEF, and LVFS were observed compared with group MI+shZFAS1." (PMID 33952724, 2021). "We found that MI+shZFAS1 could significantly reversed the changing trends of cardiac tissues morphological changes, infarction ratio, vWF expression, LVEF, and LVFS in the group MI." (PMID 33952724, 2021).
acute lung injury (5 papers, 2018 to 2025). A condition of lung damage that is characterized by bilateral pulmonary infiltrates (pulmonary edema) rich in neutrophils, and in the absence of clinical heart failure. "Together with ANGPT2, vWF is frequently regarded as a marker for endothelial damage and higher soluble plasma levels are correlated with increased mortality in acute lung injury." (PMID 30574096, 2018). "Interleukin-6, interleukin-8, surfactant protein D, and soluble tumor necrosis factor receptor I/II (sTNFr I/II), as well as ICAM-1 and VWF, have been found to be elevated in patients with acute lung injury, and their levels fluctuate rapidly in response to different ventilation strategies." (PMID 39408067, 2024).
Alzheimer disease (5 papers, 2017 to 2025). A progressive, neurodegenerative disease characterized by loss of function and death of nerve cells in several areas of the brain leading to loss of cognitive function such as memory and language. "Previous studies have suggested that von Willebrand Factor (VWF) may be implicated in the pathogenesis of Alzheimer’s disease (AD)." (PMID 40969184, 2025). "Furthermore, five proteins (IGHV3.9, PRG4, VWF, ALB and CST3) were significantly associated with ESR values, with CST3, a protein active in neurodegenerative (Alzheimer’s Disease) and demyelinating (multiple sclerosis) neurological conditions." (PMID 35033099, 2022).
anaphylaxis (5 papers, 2015 to 2024). An acute hypersensitivity reaction that occurs from exposure to an allergen. "Additionally, large quantities of substances such as dextran, aprotinin, von Willebrand factor, and biologic therapeutics can activate Fcγ receptors on mast cells and basophils via IgG, leading to IgG-mediated anaphylaxis." (PMID 39587638, 2024). "Adverse events (AEs) related to VWF/FVIII concentrates are rare but variable, ranging from urticaria, skin rashes, pruritus, oedema, phlebitis, and chest tightness to severe anaphylaxis." (PMID 25960895, 2015). "Plasma-derived VWF was administered but was complicated by anaphylaxis and no recovery." (PMID 38689620, 2024).
aortic regurgitation (5 papers, 2019 to 2024). "Finally, we were unable to measure impact of postprocedural aortic regurgitation on vWF parameters due to low incidence of moderate and severe cases." (PMID 31359325, 2019). "However, no recovery of VWF was observed in four patients with residual aortic regurgitation." (PMID 37143635, 2023).
Arthritis (5 papers, 2020 to 2025). Inflammation of a joint. "Surprisingly, a discrepancy was observed between clinical arthritis evaluation and micro-CT scan results in vWF-deficient mice, as bone destruction was severe, but clinical arthritis was relatively mild in those mice." (PMID 33203754, 2020). "We found increased VWF release/deposition in the myocardial vasculature of mice with arthritis and HF." (PMID 37500179, 2023). "Elevated PAD4-mediated neutrophil activation in arthritis could—in a vicious cycle—be a trigger for the release of additional VWF from Weibel Palade bodies facilitating the stabilization and endothelial anchorage of NET fibers fueling thromboinflammation." (PMID 37500179, 2023). "As arthritis of deeper joints (knees, elbows, hips, and shoulders) was assessable by micro-CT scan but not by clinical evaluation, we hypothesized that vWF-deficient mice had more septic arthritis in deeper joints than superficial joints." (PMID 33203754, 2020).
Autoimmunity (5 papers, 2020 to 2023). The occurrence of an immune reaction against the organism's own cells or tissues. "Moreover, the patients herein studied showed physiological VWF levels (~143%), but they were continuously increasing (up to 198%) before relapse, causing a higher susceptibility to infections, autoimmunity or malignancy." (PMID 38068357, 2023).
bacterial pneumonia (5 papers, 2014 to 2024). Acute infection of the lung parenchyma caused by bacteria (e.g., Streptococcus pneumoniae, Haemophilus influenzae, Chlamydia pneumoniae, Mycoplasma pneumoniae, and Legionella pneumophila). "We have previously found that bacterial pneumonia is associated with an increased intensity of IHC staining for VWF in the endothelium of pulmonary vessels." (PMID 39408067, 2024). "We have previously found that bacterial pneumonia is associated with increased intensity of immunohistochemical (IHC) staining for VWF in the endothelium of pulmonary vessels." (PMID 37632023, 2023). "In another Gambian study, CRP, lipocalin-2 and vWF were associated with pediatric bacterial pneumonia using a composite diagnosis based on radiography, blood culture, and WBC count." (PMID 26366571, 2015). "Interestingly, bacterial pneumonia and ventilator support are among factors associated with the enhanced immunostaining for VWF in the pulmonary endothelium." (PMID 35215805, 2022). "We also revealed that bacterial pneumonia was associated with increased VWF staining intensity in pulmonary arterial, arteriolar, and venular endothelium, while lung ventilation was an independent predictor of increased VWF immunostaining in arterial endothelium." (PMID 35215805, 2022). "The plasma concentrations of Lpc-2, CRP, and vWF in children with a positive blood culture or with “end point” consolidation on their chest radiograph (probable bacterial pneumonia) were significantly higher than in children with no consolidation and a low white blood cell count (P < .01)." (PMID 24696240, 2014).
brain injury (5 papers, 2017 to 2025). Acute and chronic (see also brain INJURIES, CHRONIC) injuries to the brain, including the cerebral hemispheres, CEREBELLUM, and brain STEM. "Of note, whereas platelet-derived VWF is largely dispensable for normal hemostasis and thrombosis in mice, we showed that it can actively contribute to ischemic brain injury via a mechanism that is GPIbα-dependent." (PMID 31921147, 2019). "Electrical stimulation also increased the number of CD34+ cells and vWF+ vascular cells in the injured hippocampus, which was correlated with vascular remodeling after brain trauma." (PMID 29201537, 2017). "VWF is promising as a monitoring marker of systemic injury in brain trauma or critical diseases." (PMID 38075262, 2023). "The precise mechanisms underlying the pathophysiological involvement of the VWF-GPIbα axis in ischemic brain injury are not yet fully elucidated but available data strongly points toward an intricate process that includes both thrombotic and inflammatory pathways." (PMID 31921147, 2019).
coronary stenosis (5 papers, 2017 to 2022). Narrowing of the coronary artery lumen diameter. "Total plasma levels of vWF in CAD patients were also associated with the severity of coronary stenosis and presented prognostic value for major adverse cardiovascular events." (PMID 36362368, 2022). "vWF can activate platelets to release coagulation substances for participating in platelet aggregation, thrombosis, and AS plaque formation, thereby resulting in coronary stenosis, insufficient blood supply, and decreased cardiac function." (PMID 35935588, 2022). "At pathological conditions found in coronary stenosis, VWF can undergo a coil-stretch transition." (PMID 30083534, 2018).
Cushing syndrome (5 papers, 2022 to 2025). Cushing's syndrome (CS) encompasses a group of hormonal disorders caused by prolonged and high exposure levels to glucocorticoids that can be of either endogenous (adrenal cortex production) or exogenous (iatrogenic) origin. "Cushing’s syndrome, which is due to excess levels of endogenous glucocorticoids, is associated with elevated levels of procoagulant Factor VIII, Factor IX and von Willebrand Factor." (PMID 34986821, 2022). "The hypercoagulable state observed in patients receiving cortisone or those with Cushing syndrome is characterized by elevated factor VIII levels, reduced fibrinolysis, and abnormal von Willebrand factor multimers composition." (PMID 39518744, 2024).
End Stage Liver Disease (5 papers, 2014 to 2025). Final stage of a liver disease when the liver failure is irreversible and LIVER TRANSPLANTATION is needed. "While the increased ristocetin-induced aggregation can be attributed to increased von Willebrand factor levels in end-stage liver disease, the cause for the increased response to the other agonists is unknown." (PMID 31717891, 2019). "Despite including more patients, especially with end-stage liver disease, to our knowledge, this is the first study to acknowledge platelet count, hematocrit, and vWF in the analysis." (PMID 25397410, 2014).